ANXA2P1 (annexin A2 pseudogene 1)
Synonyms: formerly LPC2A; ANX2P1; ANX2L1
Gene: Processed pseudogene on chromosome 4 (153,307,792 to 153,308,717, reverse strand). Ensembl gene ENSG00000213406.
Diseases named in the same sentence as ANXA2P1 in open-access papers:
ANXA2P1 is named in the same sentence as 8 diseases in open-access papers, as found by Europe PMC text mining. Sharing a sentence is not in itself a finding about the gene and the disease. The quoted sentences say what the papers report.
glioma (2 papers, 2017 to 2019). A benign or malignant brain and spinal cord tumor that arises from glial cells (astrocytes, oligodendrocytes, ependymal cells). "The annexin A2 pseudogenes (ANXA2P1, ANXA2P2, and ANXA2P3) are significantly upregulated in glioma and are associated with adverse outcome of glioma patients." (PMID 31681595, 2019). "Cox regression analyses suggested that ANXA2, ANXA2P1 and ANXA2P2 were the independent prognosis factors for gliomas." (PMID 29291003, 2017). "Subsequent multivariate analysis results revealed that in addition to increasing age, KPS, grade and histology, high expression of ANXA2, ANXA2P1 and ANXA2P2 (HR: 1.883, P=0.002; HR: 2.444, P<0.001; HR: 2.053, P=0.001) were also the independent prognosis factors for survival of glioma samples." (PMID 29291003, 2017). "Additionally, down-regulation of ANXA2, ANXA2P1 and ANXA2P2 might contribute to the improvement of the OS for glioma patients who received chemotherapy and radiotherapy." (PMID 29291003, 2017). "Furthermore, Kaplan–Meier curve and Cox regression analyses showed that the high expression of ANXA2 and its pseudogenes were correlated with the poor OS of glioma patients, and the aberrantly expressed ANXA2, ANXA2P1 and ANXA2P2 were the independent prognosis factors for gliomas." (PMID 29291003, 2017).
lung carcinoma (2 papers, 2022 to 2025). "ANXA2P1/miR-20b-5p/FAM241A (C4orf32) was discovered as a tumor suppressive regulatory axe in lung cancer." (PMID 39886652, 2025). "Next, three tumor suppressive ceRNA modules (ANXA2P1/miR-20b-5p/FAM241A, MIR99AHG/miR-218-5p/GPM6A, and SH3RF3-AS1/miR-34a-5p/HECW2) were analyzed to assess significance of their lung cancer survival rate prediction values." (PMID 36289596, 2022).
astrocytoma (1 paper, 2017). "GBM presented a significant higher expression of ANXA2, ANXA2P1 and ANXA2P2 than astrocytoma (A, P=0.006, P=0.030 and P=0.005, respectively) and oligodendroglioma (OD, P<0.001, P=0.004 and P<0.001, respectively)." (PMID 29291003, 2017).
gastric cancer (1 paper, 2026). A primary or metastatic malignant neoplasm involving the stomach. "However, the role of the pseudogene ANXA2P1 in gastric cancer (GC) growth and glucose metabolism remains unknown." (PMID 42003918, 2026).
glioblastoma (1 paper, 2017). The most malignant astrocytic tumor (WHO grade IV). "Meanwhile, among the four glioblastoma subtypes, ANXA2P1, ANXA2P2 and ANXA2 were found to be preferentially expressed in mesenchymal subtype and less expressed in proneural subtype." (PMID 29291003, 2017). "Among four glioblastoma subtypes, ANXA2P1 and ANXA2P2 were preferentially expressed in mesenchymal subtype and less expressed in proneural subtype." (PMID 29291003, 2017). "The results indicated ANXA2, ANXA2P1 and ANXA2P2 may be related to molecular markers of mesenchymal and proneural subtypes of glioblastomas." (PMID 29291003, 2017). "In this study, Differentially Expressed Pseudogenes (DEPs) between glioblastomas and non-tumor controls were found by bioinformatics analysis, of which the annexin A2 pseudogenes (ANXA2P1, ANXA2P2 and ANXA2P3) were significantly up-regulated, along with the parent gene annexin A2 (ANXA2)." (PMID 29291003, 2017).
tumor (3 papers, 2017 to 2025). "The ANXA2P1/miR-20b-5p/FAM241A axis provides a two-fold impact on tumor suppressor activities of cancer progression via ANXA2P1 and miR-20b-5p." (PMID 36289596, 2022). "Using the same rationale, we selected three regulatory axes for tumor suppression; these axes are designated as ANXA2P1/miR-20b-5p/FAM241A (C4orf32), MIR99AHG/miR-218-5p/GPM6A, and SH3RF3-AS1/miR-34a-5p/HECW2." (PMID 36289596, 2022). "The bioinformatics analysis suggests that the tumor suppressor ANXA2P1/miR-20b-5p/FAM241A axis may have an impact on stemness signature via miR-20b-5p." (PMID 36289596, 2022).
cancer (2 papers, 2017 to 2022). A tumor composed of atypical neoplastic, often pleomorphic cells that invade other tissues. "Seven (PA2G4P4, ATP5EP2, FTH1P3, ANXA2P3, ANXA2P1, HNRNPA1P33, and HSP90B3P) of the 14 pseudogenes that our analysis revealed as important for pan-cancer classification were previously found to be differentially expressed in various cancers." (PMID 28673244, 2017).
ANXA2P1 also shares sentences with these, for which no sentence is quoted: oligodendroglioma (1 paper).